INS (insulin)
Diseases named in the same sentence as INS in open-access papers (continued):
Sharing a sentence is not in itself a finding about the gene and the disease.
diabetes (continued). "Recent advancements in diabetes therapy, such as insulin analogues and continuous glucose monitoring, offer promising avenues to mitigate hypoglycemia risk, particularly in patients with a history of cardiovascular disease." (PMID 38022365, 2023). "The discovery of insulin in 1921 brought hope and life to millions of people who suffer from diabetes, and the 100-year studies have revealed details of the molecular actions of this amazing hormone in cells and organisms." (PMID 36445308, 2023). "Its fall after iron restriction in a diabetic rat model has also been tied to improvements in diabetes and insulin production." (PMID 36137277, 2023). "A unique, non-dietary, purging behaviour available only to individuals with T1DM or Type 2 Diabetes Mellitus (T2DM) dependent on insulin therapy is the deliberate restriction and/or omission of insulin, inducing hyperglycaemia and weight loss." (PMID 37255778, 2023). "GDM is a form of diabetes that develops during pregnancy and is characterized by elevated blood glucose levels and impaired insulin sensitivity." (PMID 37510687, 2023). "Among subjects with diabetes, 34.5% were taking metformin, 8.9% were taking insulin, and 17.7% were using other antidiabetic medications." (PMID 37153847, 2023). "We identified 7 participants with anti‐insulin antibody‐mediated labile diabetes who were potential candidates for immunosuppressive therapy, and a further 5 participants with a lesser degree of antibody‐bound insulin of possible clinical significance." (PMID 37562398, 2023). "Remarkably, despite the passage of a century, insulin and its various analogues still remain a cornerstone of diabetes treatment in those with T1DM and in patients with long-standing T2DM." (PMID 36845885, 2023). "Diabetes mellitus is a disease which is because by a defect in insulin secretion and increased blood glucose level." (PMID 37720287, 2023). "Diabetes mellitus (diabetes) is a chronic condition that impairs the body’s ability to either produce or respond to the hormone insulin, which is responsible for regulating the body’s glucose levels." (PMID 37255905, 2023). "Diabetes Mellitus Type 1 is an autoimmune disease that occurs due to the destruction of insulin-producing cells (β cells), resulting in hyperglycemia." (PMID 37242432, 2023). "Glucose homeostasis in the body is determined by four diabetes factors (DFs): insulin resistance (IR), glucose effectiveness (GE), and the two phases of insulin secretion—first phase (FPIS) and second phase (SPIS)." (PMID 37685672, 2023). "The hypoglycemic effect of banaba seems to reflect multiple mechanisms, including enhanced insulin sensitivity, by improving the expression of liver PPAR-α mRNA and adipose tissue PPAR-γ mRNA, thus reducing the risk of IGT progressing toward overt diabetes." (PMID 38099180, 2023). "We developed a curriculum for a SDM process to choose an insulin injector for insulin-naive patients with diabetes mellitus, which took place immediately before the start of the initial treatment with insulin." (PMID 37005930, 2023). "Despite this, no national or international curricula include skills/techniques/competencies required to address the health beliefs, fears and worries in accepting insulin as part of diabetes self-management." (PMID 37237318, 2023). "The person with diabetes was also placed on 30 units of insulin (ie, 70/30 premixed insulin) twice daily." (PMID 37535407, 2023). "NHS Diabetes guidelines for the perioperative management of the adult patient with diabetes recommend glucose monitoring for patients undergoing general anesthesia if the patient receives insulin and the procedure is longer than 1–2 h23,24." (PMID 36922617, 2023). "Most cases of ABCC8-dependent diabetes are misdiagnosed as other types of diabetes mellitus, and insulin is mistakenly prescribed, which can result in poor control of carbohydrate metabolism." (PMID 36836406, 2023).
diabetes (continued). "Autoimmune destruction of insulin‐producing beta cells results in Type 1 diabetes mellitus and is characterized by the presence of insulitis and beta‐cell autoantibodies and one‐third of patients develop an APS." (PMID 37305884, 2023). "Physical activity increases muscle mass and improves insulin-independent glucose uptake by the skeletal muscle, which leads to decreased glycemia and improvements in diabetes and various other complications that lead to sarcopenia." (PMID 37685565, 2023). "There are several treatment methods, such as insulin therapy and islet transplantation, to cure diabetes, although some of these methods have significant challenges." (PMID 36839746, 2023). "PCSK9 was also reported to be associated with insulin secretion and diabetes mellitus (DM)." (PMID 37012310, 2023). "To find more support for the role of RHOT1 in insulin secretion and T2D, we silenced Rhot1 in β-cells and evaluated a rodent model of diabetes." (PMID 38086799, 2023). "Only data from the T1D Exchange in the USA include comparable – but still smaller – numbers (n = 1,714;, but results cannot be directly transferred to the European environment, as, e.g., payment for insulin and diabetes supplies is different in the US." (PMID 38129890, 2023). "Diabetes is characterized as a bi-hormonal disorder, owing to the defective secretion of both glucoregulatory hormones, insulin and glucagon." (PMID 38298268, 2023). "Linkage analysis revealed numerous QTL for diabetes-related traits such as blood glucose, body weight and plasma insulin." (PMID 36614300, 2023). "STZ damages insulin-producing beta cells within the pancreas, and therefore it is commonly used to induce diabetes in laboratory animals." (PMID 38202711, 2023). "The performance of 4-hour and 24-hour MA, 3-observation and 25-observation RR, and recursive regression BG predictions are compared in the full population, patients with T1DM, and patients with type 2 diabetes mellitus with basal insulin on board." (PMID 36719713, 2023). "T1D is an autoimmune disease that requires external insulin injection and sustainable diabetes self-management (DSM) behaviors to maintain optimal glucose levels." (PMID 37121571, 2023). "No other differences were found between the patients treated with insulin vs. oral agents at diabetes diagnosis namely the presence of CKD, renal malformations, or elevated liver enzymes." (PMID 36793123, 2023). "Oral hypoglycemic agents: In recently diagnosed drug-naive diabetes patients with fasting blood sugar >200 mg, Gliclazide MR 60 mg was compared to 16 u of premixed insulin, combined with medical nutrition therapy." (PMID 36819346, 2023). "Walter R. Campbell and Andrew A. Fletcher of the TGH Department of Medicine (directed by Duncan A. Graham) successfully treated more than fifty patients with insulin before the end of 1922 at the Diabetes Ward of TGH." (PMID 36585966, 2023). "Since a 2014 meta-analysis, several randomized controlled trials (RCTs) evaluating the effect of vitamin E intake on glycemic indices and insulin resistance in adults with diabetes have reached inconsistent conclusions." (PMID 36800965, 2023). "As anticipated with the progressive nature of the disease after 2 years in the study, half of the patients who had diabetes for >10 years at baseline were taking OAD + insulin and those who had diabetes for ≤10 years at baseline were predominantly on OADs." (PMID 36722454, 2023). "Clinically overt diabetes only occurs when both insulin action and secretion deteriorate to such a degree that glucose homeostasis cannot be maintained." (PMID 37685672, 2023). "Today’s diabetes-oriented telemedicine systems can gather and analyze many parameters like blood glucose levels, carbohydrate intake, insulin doses, and physical activity levels (steps)." (PMID 37115601, 2023).
diabetes (continued). "Earlier research indicates that individuals critically ill with both diabetes mellitus and COVID-19 exhibited elevated insulin needs and experienced a less favourable duration within the target blood glucose range during the peak of the inflammatory response." (PMID 38192935, 2023). "Patients with diabetes remission were younger (p = 0.004), had a shorter duration of diabetes preoperatively (p < 0.001), used less preoperative insulin (p < 0.001), had fewer oral hypoglycaemic medications (p < 0.001), and also had lower HbA1c (p < 0.001)." (PMID 37241216, 2023). "Long-term Arg therapy has been shown to prevent or delay the onset of T2DM and maintain long-lasting effects on diabetes incidence, insulin secretion, oxidative stress, and endothelial function in high-risk individuals." (PMID 38004100, 2023). "Patients showing diabetes mellitus with decreased insulin secretion and increased insulin resistance must be considered for magnetic resonance imaging and/or endoscopic ultrasound immediately." (PMID 37509329, 2023). "Diabetes mellitus (DM) constitutes a cluster of metabolic disorders characterized by hyperglycemia resultant from anomalies in insulin secretion, insulin responsiveness, or a combination thereof." (PMID 37893201, 2023). "His mother had diabetes and was on insulin treatment; she also had mental health issues with family-related social stressors." (PMID 36733550, 2023). "Insulin (Humulin R®) is a widely prescribed medication for managing the symptoms of diabetes by promoting glucose uptake into cells and decreasing glucose levels in the body." (PMID 38389818, 2023). "Diabetes Mellitus (DM) is a common metabolic disease characterized by chronic hyperglycemia resulting from defects in insulin secretion, action or both." (PMID 37540642, 2023). "Insulin is produced or used improperly in diabetes mellitus (DM) and endocrine system metabolic disorders." (PMID 37763342, 2023). "Diabetes, as a metabolic disorder featured by increased blood glucose, result from defective insulin function, impaired insulin secretion, or both, which has increased mortality in recent years." (PMID 36918530, 2023). "Diabetes is related to insulin resistance and insufficient insulin secretion and poses a serious threat to safety, human life, and health." (PMID 37400673, 2023). "We have surveyed patients’ perceptions of insulin therapy in diabetes self-management to understand their unmet needs." (PMID 36828942, 2023). "Transdermal insulin delivery patches are used to deliver insulin across the skin and into the bloodstream to treat diabetics." (PMID 37109736, 2023). "A chronically elevated leptin level impairs post-prandial GLP-1 release and insulin sensitivity, contributing to hyperinsulinaemia in patients with normal fasting plasma glucose (pre-diabetes) and promoting the development of T2DM and NASH." (PMID 37233716, 2023). "Technological advancements in diabetes care, such as insulin pumps, continuous glucose sensors, and closed loop systems, offer hope and tools to improve outcomes in diabetes care." (PMID 37901094, 2023). "Sulfonylureas, thiazolidinediones, metformin, and insulin are some oral hypoglycemic agents used to treat diabetes." (PMID 36983154, 2023). "One of the characterizing traits of diabetes is the failure of functional β-cells to modulate insulin secretion to offset increasing insulin resistance, driving disease development." (PMID 36935456, 2023). "Of the two main types of diabetes, type I diabetes is an autoimmune disorder in which insulin secreting beta cells in the pancreas are destroyed by the immune system." (PMID 36830072, 2023). "Total distance traveled was significantly increased in Dia + CM and Dia + INS groups compared to the diabetes group." (PMID 37081849, 2023). "The discovery of insulin by Banting, Best, Collip, and Macleod in 1921 revolutionized diabetes care, offering hope to countless individuals." (PMID 38077372, 2023).
diabetes (continued). "Diabetes results from dysfunction or complete destruction of insulin-producing β cells within pancreatic islets of Langerhans." (PMID 37180045, 2023). "Reportedly, arsenic-contaminated water leads to injury and apoptosis of the beta-cells of the pancreas, disrupting insulin production and function, ultimately resulting in insulin-dependent diabetes mellitus." (PMID 37759824, 2023). "Compared to diabetes controls, we also discovered that insulin promoted 18F-FDG uptake in B16 tumor tissue." (PMID 37884546, 2023). "It has also been shown that NF-κB receptor activator (RANKL) is a potent stimulator of NF-κB and that systemic or hepatic blockade of RANKL signaling leads to significant improvements in hepatic insulin sensitivity and prevents the development of diabetes." (PMID 37056675, 2023). "Current guidelines suggest the use of insulin as basal bolus or continuous subcutaneous insulin infusion (CSII) in Type 1 diabetes mellitus (T1DM) and for hospitalized patients." (PMID 36676765, 2023). "Studies showed that medical students possessed shortcomings in certain aspects of diabetes management that included insulin treatment options, diabetic dietary counseling, and management of hypoglycemia and perioperative diabetes management guidelines." (PMID 37046268, 2023). "The evaluation of self-care showed greater adherence to the activities of taking insulin injections and medications as recommended, taking the indicated number of diabetes pills, and following a healthy diet." (PMID 37436236, 2023). "Of the 93 patients, diabetes was present in 52 (55.9%) patients before surgery, and 20 (38.5%) of the 52 had already received insulin therapy." (PMID 36860372, 2023). "Residual insulin secretion is present in 60% of T1D with ≥ 3 years of diagnosis in routine diabetes care." (PMID 36935525, 2023). "A prospective pilot study included 15 lung transplant patients (mean age 58.6 years; 53.3% men; 73.3% with pre-transplantation diabetes) managing hyperglycemia with insulin." (PMID 38993859, 2023). "The main characteristics of diabetes are insufficient insulin secretion and/or disturbed cellular insulin signaling (insulin resistance), resulting in chronic hyperglycemia." (PMID 36470401, 2023). "The use of microneedles in transdermal drug delivery has shown promising results in various areas of drug therapy, including insulin delivery for diabetes, vaccine delivery, and pain management." (PMID 37397493, 2023). "GCK-MODY is a specific type of diabetes mellitus characterized by autosomal dominant inheritance, which usually occurs before 25 years of age and exhibits a defect in glucose-stimulated insulin secretion." (PMID 37082200, 2023). "Pre-clinical study has also revealed that aerobic exercise can improve glucose and lipid metabolism in male rats with obesity or diabetes by decreasing levels of fasting blood glucose, insulin, TG, and LDL cholesterol." (PMID 37900128, 2023). "Buettner proposed “leptin therapy” as a superior alternative to insulin for the management of type 1 diabetes mellitus." (PMID 37241229, 2023). "Because these conditions run in families, genome-wide association (GWA) studies have been performed to assess fasting insulin, hyperinsulinaemia or diabetes." (PMID 37420130, 2023). "Patients with diagnosed diabetes mellitus (#1, #2, and #5) presented poor metabolic control at this last visit, even with multiple-dose insulin therapy in two of the cases, with mean HbA1c levels of 8.6 ± 1.6%." (PMID 38068396, 2023). "In the T1D Exchange (T1DX) Registry in the USA, 50% of young children were using insulin pumps compared to 74% in the Prospective Diabetes Follow-up Registry (DPV) in Germany and Austria." (PMID 40303252, 2023). "Phenolic components in commercial insulin preparations also reduce the effectiveness of diabetes therapy due to the cytotoxic effect." (PMID 36835194, 2023).
diabetes (continued). "In conclusion, compared with traditional insulin pens, the use of needle-free syringes and enhanced management can effectively reduce the fasting blood glucose of patients with early-onset type 2 diabetes mellitus treated with premixed insulin." (PMID 36864833, 2023). "In a GPER deficient female mouse model, it was found that there is an insufficient amount of insulin is producing in them that lead to the development of diabetes mellitus." (PMID 36782201, 2023). "HOMA and QUICKI indices are robust, accurate, and reproducible methods that appropriately predict changes in insulin sensitivity after therapeutic interventions as well as the onset of diabetes." (PMID 37509329, 2023). "The concomitant use of insulin and a DPP-4 inhibitor was recommended by a joint position statement of the American Diabetes Association (ADA) and the European Association for the Study of Diabetes (EASD) in the therapeutic algorithm for T2DM management." (PMID 38021574, 2023). "Patients treated with insulin pens and those with uncontrolled diabetes, as evidenced by a higher level of HbA1c, were more likely to develop diabetes distress than their peers." (PMID 37193469, 2023). "Twelve studies reported the duration of diabetes in diabetes patients, and ten reported the time of insulin injection." (PMID 37976255, 2023). "Prices for insulin around the world, including in developing countries, remain high; the World Health Organization has identified improved global access to insulin and other diabetes therapies as a key public health priority in the coming decades." (PMID 37971985, 2023). "Together, oxidative and endoplasmic reticulum stress adversely affect the function of the pancreas and impair the ability of pancreatic insulin release in response to glucose loading, leading to the development of diabetes." (PMID 36674879, 2023). "Diabetes during pregnancy manifests as a disorder affecting the secretion and function of insulin, leading to hyperglycemia." (PMID 37469977, 2023). "Relatively speaking, regular diabetes care mainly focuses on diet, exercise, and insulin injection guidance, which is more generalized and limited, and is more often used for primary care or basic specialized care." (PMID 38187353, 2023). "Diabetes mellitus, a condition in which the body’s ability to produce insulin is impaired, and osteoarthritis (OA), a painful degeneration of joint cartilage, are both serious conditions that affect millions of people in the United States (U.S.)." (PMID 37255905, 2023). "It is well known that diabetes mellitus (DM) is a progressive metabolic disease caused by a relative or absolute deficit in the secretion of insulin and/or deterioration in its signaling, thus resulting in the appearance of hyperglycemia and disturbed metabolism of carbohydrates, fats and proteins." (PMID 37754589, 2023). "Diabetes mellitus is defined as a group of metabolic disorders characterized by high blood glucose levels brought on by abnormalities in insulin production, insulin action or both and by alterations in fat, protein and carbohydrate metabolism." (PMID 37623721, 2023). "Diabetes is a heterogeneous group of disorders characterized by hyperglycemia due to an absolute or relative deficit in insulin production or action." (PMID 37687031, 2023). "For people with diabetes, insulin use had been taken as a routine, so even simple rewards (eg, cumulative points in the form of grades and badges) encouraged people with diabetes to practice glycemic control." (PMID 38133907, 2023). "As SSTR5 is expressed in pancreatic β‐cells and intestinal L‐cells, studies have suggested that SSTR5 regulates glucose tolerance through insulin and incretin secretion, thereby having a prominent role in diabetes." (PMID 36585794, 2023). "The diabetes team randomly and blindly manipulated post-lunch glucose levels by subcutaneous injection of either rapid-acting insulin or 0.9% NaCl solution before lunch." (PMID 37091855, 2023).